MYC (MYC proto-oncogene, bHLH transcription factor)
Diseases named in the same sentence as MYC in open-access papers (continued):
Sharing a sentence is not in itself a finding about the gene and the disease.
tumor (continued). "Rihawi and colleagues have found the presence of ALK rearrangement coupled to MYC amplification in tumour and CTCs from the same patient, suggesting a role for MYC for primary resistance to crizotinib." (PMID 35372000, 2022). "Upregulated MYC promotes the initiation and progression of cancers by controlling cancer cell-intrinsic oncogenic signaling pathways, tumor microenvironments (TME), and immune surveillance." (PMID 35267473, 2022). "To verify that MYCMI-7 inhibits MYC:MAX dimerization in tumor cells, we utilized the split Gaussia princeps luciferase (GLuc) assay, with GLuc fragments GLuc1 and GLuc2 fused to MYC (or MYCN) and MAX, respectively, in HeLa cells." (PMID 36874405, 2022). "Apart from enhanced transcription, tumor cells also maintain high MYC protein levels by evading protein turnover via the PI3K/AKT pathway." (PMID 35883689, 2022). "Previous studies have found that the inhibition of MYC-related and other eRNAs by using ASOs can effectively inhibit tumor cell progression, suggesting that eRNAs can be helpful as therapeutic targets." (PMID 35039581, 2022). "According to the higher tumor burden in the spleen in VK*MYC bearing mice, Tregs displayed here also a more activated phenotype." (PMID 34584204, 2022). "For example, CLK2 inhibitor T-025 inhibits tumor cell proliferation via inducing exon skipping in MYC-driven cancers." (PMID 35860803, 2022). "Activation of MYC also promotes the recruitment of mast cells to tumor sites, which is required for tumor angiogenesis and macroscopic expansion." (PMID 36313280, 2022). "In summary, this study investigated the influence of diet (30% CR, NCD, or HFD) on tumour progression in the transplant Vk*MYC (Vk14451-GFP)-C57BL/6J pre-clinical model of MM." (PMID 35908046, 2022). "MYC has been shown to be upregulated in HLRCC tumors and drugs that downregulate MYC suppress the growth of HLRCC tumor cell lines." (PMID 36455002, 2022). "RBM25 acts as a tumor suppressor and regulator of MYC activity by controlling the splicing of the MYC inhibitor BIN1." (PMID 36147313, 2022). "It is also well known that suppression of the MYC oncogene induces cellular senescence in diverse tumor types, including lymphoma, osteosarcoma and hepatocellular carcinoma." (PMID 35328482, 2022). "Mechanismly, BET inhibitors exert their anti-tumor effect mainly through the inhibition of MYC, a downstream gene of BRD4, in many cancer types." (PMID 36187481, 2022). "c-MYC is an oncogene that can affect tumor cell proliferation, migration, invasion, metabolism, ribosome production, etc.." (PMID 36233342, 2022). "Ep5 from a luminal-HER2-type tumor showed a luminal-specific pattern of gene activity (KRT8/18) as well as greater ERBB2, GRB7, and MYC activities, which are often coamplified in breast cancer." (PMID 35676392, 2022). "MYC, a transcriptional regulator overexpressed in various cancers, appears to play a direct role in preventing immune cells from effectively attacking tumor cells." (PMID 35958876, 2022). "Previous studies have shown that the effects of MYC on the tumor immune microenvironment differ between cancer types." (PMID 36323660, 2022). "We studied transgenic mice expressing MYC oncogene (hiMYC mice) to induce tumorigenesis in the mouse prostate and discovered that transgenic overexpression of miR-32 resulted in increased tumor burden as well as a more aggressive tumor phenotype in this model." (PMID 35228520, 2022).
tumor (continued). "We identify NFκB, AP-1, and MYC as mediators of this transition, and show that the gene expression profiles of tumor cells and infiltrating microglia are consistent with abundant pro-inflammatory signaling between these populations." (PMID 35803925, 2022). "In vivo studies show that the treatment of orthotopic ATRT xenografts with the BET inhibitor, JQ1, mimics the effects observed when MYC is directly depleted and ultimately reduces tumor growth." (PMID 35892904, 2022). "Overexpression of MYC can activate an impaired DNA damage response, which leads to genomic instability and tumor progression." (PMID 36057607, 2022). "GSVA analysis based on hallmark gene sets showed that tumor-promoting signaling pathways were inhibited in the PTX+CKI group, such as TGF beta signaling, MYC targets variant 1 and MYC targets variant 2 (PTX+CKI vs. saline and PTX+CKI vs. PTX)." (PMID 36389835, 2022). "Incidentally, we also explored the relationship between MYC signaling and cell proliferation and tumor stemness." (PMID 36299592, 2022). "Clinical prognosis is particularly poor for tumor subtypes with activating aberrations in the MYC pathway, creating an urgent need for novel therapeutic targets." (PMID 35439169, 2022). "Amongst differentially expressed genes, we found increased expression of the c-MYC proto-oncogene (MYC) and its downstream targets in tumor samples." (PMID 36139061, 2022). "The dominance of the pro-survival or pro-apoptotic effect is likely context dependent, and the MYC S146L-imbued survival benefit only arises following the establishment of malignancy and subsequent tumor evolution." (PMID 36018850, 2022). "MYC-positive cells are observed between myofibers at the periphery of the tumor, and there were myofibers that were completed surrounded by MYC-positive cells." (PMID 35574356, 2022). "To analyze the effect of MYC signaling on the immune cells and the tumor microenvironment, we calculated the infiltration levels of the 10 immune cells using the MCP counter R package and performed a statistical test with a t-test." (PMID 36299592, 2022). "It was demonstrated that MYC regulates virtually all stages of lipogenesis, which is required for the initiation and maintenance of tumor growth." (PMID 35501901, 2022). "Different reports have highlighted the importance of c-MYC during the multidrug resistance phenotype in different tumour types." (PMID 35326669, 2022). "Of note, at 12 weeks of age, low expressions of c-MYC, p-IKKα/β, and p-p65 were evident in the pre-malignant stage of tumor initiation." (PMID 35589707, 2022). "For instance, TAZ overexpression in hematological malignancies translates into a tumor-suppressing factor by inhibiting MYC." (PMID 36230758, 2022). "In a liver cancer model, MYC upregulation was shown to induce innate cell infiltration as well as enhanced checkpoint inhibitor expression by tumour cells, which altogether led to increased angiogenesis, chemoresistance, and proliferation of tumour cells." (PMID 36358867, 2022). "Although known as a positive regulator of the MYC proto-oncogene, it is the previously reported FBP participation in a MYC-repressing complex with FIR that is consistent with a tumor-promoting scenario." (PMID 35158934, 2022). "A prior study demonstrated that m6A modifications of c-MYC mRNA promote glycolysis and tumor growth in LUAD." (PMID 35078505, 2022). "Previously, MYC was shown to regulate the expression of an immune checkpoint protein on the surface of tumor cells, the adaptive immune checkpoint PD-L1 (programmed death ligand 1)." (PMID 36582521, 2022).
tumor (continued). "The acidic pHe is mainly a result of aberrant stromal or tumor cell metabolism that favors glycolysis driven by hypoxia or the activity of oncogenes such as MYC." (PMID 36380966, 2022). "The results showed that the tumor immune dysfunction score was significantly lower in the MYC signaling activation group when compared to the MYC signaling inhibition group." (PMID 36299592, 2022). "While tumors arising through the disruption of tumor suppressors only generated micrometastatic nodules in the omentum, the addition of MYC resulted in macrometastatic disease and ascites formation." (PMID 35082152, 2022). "These molecules can efficiently inhibit MYC expression and tumor cell viability by stabilizing target mRNA–eIF4A interaction that directly prevents translation." (PMID 35303910, 2022). "They act as tumor suppressors by inhibiting the expression of oncogenes, such as MYC, RAS, and HMGA2." (PMID 35806250, 2022). "FBXO28 has been previously shown to regulate MYC activity in cancer cells, and was found in the same study to be upregulated on the mRNA level in various tumor entities." (PMID 36115843, 2022). "A hallmark enriched pathway analysis suggested that the expression of NFS1 was positively correlated with the MYC pathway, and NFS1 expression was positively correlated with MYC expression in our CRC tumor tissues and in tissues from the TCGA database." (PMID 35221331, 2022). "c-MYC contributes to tumor progression and metastasis and induces cancer stemness properties in multiple neoplasms." (PMID 35681547, 2022). "We found that MYC expression was significantly correlated with tumor size, and pathological T. MG562507.1 (T5) was significantly correlated with family history." (PMID 36052265, 2022). "For example, both c-MYC and K-Ras-activating mutations were shown to increase NRF2 expression and promote tumor progression." (PMID 36310172, 2022). "This algorithm correctly classified all MYC+ tumor cases (cases 1–31 from cohort 2) including the two cases with cryptic rearrangement (cases 21 and 54), but misclassified four MYC− cases as MYC+ (cases 44, 49, 51, and 55) because these had elevated GPS." (PMID 36051032, 2022). "For example, activation of the proto-oncogenes MYC, ZNF217, and WT1 is associated with DEGs expressed by all three tumor types examined in this study, and therapeutic approaches to inhibition of all three in cancers are being developed." (PMID 36099287, 2022). "Since expressions of c-MYC, cyclin D1, and vimentin were reduced after TUBB4A KO, we analyzed the mRNA expression of β-catenin-targeted genes c-Myc, Ccnd1, and Vim in microdissected tumor cells." (PMID 35589707, 2022). "In human cancers mutations present in the PVT1 promoter alter the tridimensional structure of the TAD and allow the enhancers to promote c-MYC transcription favoring tumor progression." (PMID 35090471, 2022). "The tumor survival is mediated by HIF-1α in a hypoxic environment through inhibition of MYC, a transcriptional factor regulating mitochondrial mass and oxygen consumption in several human cancers." (PMID 35798726, 2022). "With system biological analysis of the network constructed by cancer related pathways and DEGs, we found that MYC is a key gene in the network of eucalyptol’s anti-tumor mechanism." (PMID 36331666, 2022). "Our previous work showed the therapeutic potential of BPTF in a PDA mouse model driven by c-MYC (Ela1-c-MYC), reducing cell proliferation and tumour growth." (PMID 35326669, 2022).
tumor (continued). "Moreover, decreased MYC protein levels may potentially have downstream effects which render MM cells more susceptible towards the activity of immune cells, since MYC also regulates anti-tumor immunity through CD47 and PD-L1 in vivo." (PMID 35692781, 2022). "Taken together, due to the salient incongruity between fetal PGCs and MYC tumor cells, which is most likely based on the highly dynamic epigenome of PGCs, hereinafter we aimed to gain deeper insights into the deregulated transcriptomes of murine RT." (PMID 35318328, 2022). "It has been demonstrated before that IGF2BP1 enhances tumor cell proliferation through a m6A-dependent stabilization of MYC mRNA, one of its major known oncogenic targets." (PMID 35565249, 2022). "The study finally identified that AMBRA1 interacts with the phosphatase PP2A and enhances its phosphatase activity on the proto-oncogene c-MYC, which further prevents tumorigenesis and tumor hyperproliferation." (PMID 36237336, 2022). "Several studies found that BPTF is required for c-MYC transcriptional activity and is associated with EMT as well as tumor progression." (PMID 35646694, 2022). "As expected, MYC and OTX2, the two well-established oncogenic driver TFs of G3-MB, are revealed as subtype-specific SE-associated oncogenes of G3-MB tumor tissues." (PMID 36273157, 2022). "Following up from these results, we showed that tigecycline and venetoclax acted synergistically against tumor xenografts derived from MYC/BCL2 double‐hit lymphoma." (PMID 36214609, 2022). "Nevertheless, by combining MYC inactivation with anti-PD-L1 therapy, we significantly delayed tumor recurrence, extending median survival by ~25% compared to the isotype treated group (69 days in MYC-OFF + isotype antibody vs. 88 days in MYC-OFF + anti-PDL1)." (PMID 35760778, 2022). "The sensitivity and specificity values relative to the MYC IHC score based on staining in at least 50% of the tumor cells were 0.65 and 0.65, respectively." (PMID 35267654, 2022). "The released JQ1 inhibits the growth of triple-negative breast cancer by inhibiting the BRD4-c-MYC axis and suppressing the expression of PD-L1, which facilitates the activation of T cells in tumor tissue." (PMID 36119019, 2022). "The high levels of DNA replication stress result in addiction to ATR/CHK1 signalling since this allows MYC driven tumour cells to survive high levels of genomic instability." (PMID 36240065, 2022). "This further suggests the importance of MYC signaling in mediating the tumor immunosuppressive microenvironment." (PMID 36299592, 2022). "Overexpression of MYC oncogene, while inducing aggressive tumor behavior, in fact leads to increased chemosensitivity." (PMID 36396656, 2022). "Building on observations of Msi1 deletion in a syngeneic mouse Myc-amplified G3 MB model, we further determine if similar tumor suppressive effects would be achievable in human models of MYC-amplified G3 MB." (PMID 36473869, 2022). "Depletion of G9a abrogates the binding of MYC to chromatin, reverses the repression of MYC-suppressed genes, and hinders tumor growth." (PMID 35203421, 2022). "Both STAT3 and MYC expression are described as being involved in tumor formation, cancer metabolism and even metastasis." (PMID 36555426, 2022). "Overexpression of MYC suppresses innate immunity, blocking induction of interferon signalling and tumour growth inhibition." (PMID 36242657, 2022). "It was recently demonstrated that cell competition is able to drive tumor initiation in different Drosophila organs, but what happens to cancer cells if some start to up-regulate MYC while contributing to an expanding tumor?" (PMID 36704198, 2022). "The wide implication of MYC family oncoproteins in both tumor initiation and maintenance suggests that therapeutic targeting MYC expression/activity should achieve a significant clinical efficacy." (PMID 35013218, 2022).
tumor (continued). "This coincided with the activation of many signals related to tumor development, such as the MYC signaling pathway, E2F target, oxidative phosphorylation, interferon response, and mTOR signaling pathway." (PMID 36569894, 2022). "To explore the functional consequences of MYC-induced repression of MHC-I in tumor cells, we established a coculture model system." (PMID 35499080, 2022). "We demonstrate that MYC suppresses immune cell infiltration into tumors by repressing IFN/STING signaling in a tumor cell-intrinsic manner." (PMID 36323660, 2022). "Intriguingly, ectopic MYC in MET tumours increases expression of the Mki67 proliferation marker, and switches them into loss of Afp, Spp1, Gpc3, Epcam accompanied by an increase in Hgma1, Vim, and Hep-Par1 levels." (PMID 36433941, 2022). "Among the target genes downregulated by DRAK1 overexpression, MYC has been reported to have sustained induction by paclitaxel leading to tumor progression of PDAC." (PMID 35194034, 2022). "MYC is a member of a proto‐oncogenic TF family, which is deregulated in the majority of human and canine tumours, including hOSA." (PMID 36054794, 2022). "MYC overexpression thus counters tumor growth inhibition by a Stimulator of Interferon Genes (STING) agonist via suppressing induction of interferon signalling." (PMID 36323660, 2022). "Our study also reveals that this exacerbation of tumour progression is accompanied by an enrichment of the proliferative MYC gene signature and an escape of p16INK4A-mediated oncogene-induced senescence." (PMID 35354467, 2022). "One-third of these overlapping genes are upregulated in MYC tumor cells and are related to GO terms such as regulated exocytosis, response to cytokines or interferon-gamma, and antigen presentation." (PMID 35318328, 2022). "Here, we confirm the high NLRP3 and PYCARD expression in tumor samples (50% and 31%, respectively) as well as an overexpression of CyclinD1 and MYC, (48% and 32%, respectively)." (PMID 35745570, 2022). "This blockage leads to increased MYC degradation, impaired MYC-mediated gene expression, and suppressed tumor growth in vivo." (PMID 35908121, 2022). "Many colorectal cancers (CRC) develop loss-of-function mutations in the tumour suppressor APC (adenomatous polyposis coli), resulting in up-regulated MYC mRNA levels and proto-oncogenic activity, which has been shown to contribute to tumour initiation." (PMID 35311890, 2022). "Multiple studies have demonstrated that MYC functions as a transcriptional inhibitor of tumor suppressor genes, such as miR-34, miR-26, miR-15/-16, miR-23, miR-29, Let-7, and miR-126*." (PMID 36672841, 2022). "The change in MYC protein expression directly correlated with the change in Ki-67 expression and the change in tumor volume on CT scan." (PMID 36194476, 2022). "Of particular note, MYC is also frequently deregulated in these cancer types and meanwhile these tumor cells rely on high levels of MYC for survival." (PMID 35013218, 2022). "Together, our data reveal that MYC suppresses innate immunity and facilitates tumor immune escape, explaining the poor immunogenicity of MYC-overexpressing TNBCs." (PMID 36323660, 2022).